IGF2 (insulin like growth factor 2)
Diseases named in the same sentence as IGF2 in open-access papers (continued):
Sharing a sentence is not in itself a finding about the gene and the disease.
ovarian carcinoma (continued). "Previous studies suggested that IGF2 participate in the malignant behavior of ovarian cancer through PI3K/Akt signal pathway." (PMID 29212217, 2017). "By using this cut score, the size of the IGF2-high group approximates the fraction of ovarian cancer patients expected to have intrinsically drug resistant tumors, manifested by progression during or shortly after completing chemotherapy." (PMID 24932685, 2014). "The clinical relevance of our findings is supported by the validation of IGF2 as a poor prognostic factor for early recurrence and death in ovarian cancer patients." (PMID 24932685, 2014). "In a genetically diverse panel of ovarian cancer cell lines, the IGF2 mRNA levels measured in cell lines resistant to various microtubule-stabilizing agents including Taxol were found to be significantly elevated compared to the drug sensitive cell lines." (PMID 24932685, 2014). "The purpose of this study was to validate IGF2 as a potential therapeutic target in drug resistant ovarian cancer and to determine the efficacy of targeting IGF2 in vivo." (PMID 24932685, 2014). "In particular, IGF2 gene expression was 300-fold higher in ovarian cancer tissue than in normal ovarian tissue and expression was higher in advanced stage poor prognosis cancers." (PMID 25601855, 2014). "The consensus sequence contains a single CpG dinucleotide whose methylation is strongly positively correlated with expression levels of IGF2 in ovarian cancer (Huang and Murphy, in press)." (PMID 23775149, 2014). "We identified a sequence within IGF2 intron 3 that matches this consensus motif, and our preliminary analysis showed a strong relationship between methylation of this putative binding site and expression of IGF2 in ovarian cancer tissues." (PMID 23745176, 2013). "Positive correlation between methylation and IGF2 transcription in primary ovarian cancers suggests the potential for epigenetic therapies in controlling IGF2 overexpression in this disease." (PMID 23745176, 2013). "HEY cells have the lowest IGF2 transcript levels, as do many other established ovarian cancer cell lines, while the other two lines exhibit higher IGF2 expression." (PMID 23745176, 2013). "The growth-stimulatory function of IGF2 likely confers a substantial advantage to malignant cells, given the ubiquity of IGF2 overexpression in ovarian cancer." (PMID 23745176, 2013). "Furthermore, in ovarian cancers, insulin receptors are preferentially overexpressed as IR-A isoforms, which specifically favors binding by IGF-2." (PMID 38396692, 2024). "The potential clinical implications are supported by the finding that serum levels of IGF-1, IGF-2, and PAPP-A2 are associated with patient prognosis and may find use as biomarkers for ovarian cancer." (PMID 38396692, 2024). "An animal experiment shows that dexmedetomidine effectively inhibits insulin-like growth factor 2 (IGF2) signaling pathway activation in ovarian cancer rats, thereby enhancing their immune function and suppressing the invasion and migration of ovarian cancer cells." (PMID 39295870, 2024). "IGF2 mediates the inhibition of exosomal miR-543 on the proliferation of ovarian cancer cells." (PMID 39759028, 2024). "Upregulating IGF2 could enhance the proliferation, migration, and invasion capacities of ovarian cancer cells." (PMID 35754835, 2022). "DEX can effectively inhibit the activation of IGF2 signal pathway, improve the immune function of ovarian cancer rats, inhibit the invasion and migration of ovarian cancer cells, and significantly increase the percentage of CD4+, CD8+ and the ratio of CD4+/CD8+." (PMID 35586059, 2022). "Several target genes of miR-140-5p have been identified, including platelet-derived growth factor receptor A (PDGFRA) in ovarian cancer, insulin-like growth factor 2 mRNA-binding protein 1 (IGF2BP1) in cervical cancer, and YES proto-oncogene 1 (YES1) in gastric cancer." (PMID 30962263, 2019).
ovarian carcinoma (continued). "This proof-of-principle study, demonstrating that IGF2 modulation overcomes multiple Taxol resistance mechanisms, now forms the basis for preclinical testing of IGF2 targeting agents in combination with standard combination ovarian cancer treatment regimens." (PMID 24932685, 2014). "We examined the impact of IGF2 knockdown on not only Taxol’s effects, but also the response to non-taxane microtubule interacting drugs, and other drugs commonly used in the treatment of ovarian cancer." (PMID 24932685, 2014). "Thus, IGF2 knockdown restored the efficacy of Taxol in this in vivo model of drug resistant human ovarian cancer, consistent with the effect observed in tissue culture." (PMID 24932685, 2014). "Thus, we have identified IGF2 to be a promising therapeutic target for overcoming drug resistance in ovarian cancer, and further translational studies are merited to bring this fundamental discovery to the clinic." (PMID 24932685, 2014). "Several studies also implicate over-expression of IGF2 in colon cancer and in ovarian cancer." (PMID 19732452, 2009). "Moreover, we quantified IGF2 and miR-543 mRNA levels in ovarian cancer and paracancerous tissues." (PMID 35391781, 2022). "In addition, following Taxol treatment, IGF2 mRNA levels progressively increased in ovarian cancer." (PMID 28521298, 2017). "In this prospective, longitudinal study of 107 women with ovarian cancer and ascites accumulation, we determined corresponding serum and ascites levels of IGF-1, IGF-2, PAPP-A, PAPP-A2, STC1, and STC2 and assessed their relationship with mortality." (PMID 38396692, 2024). "Increased DANCR expression was also reported in ovarian cancer (OC) and was shown to promote carcinogenic mechanisms mediated by IGF2 (insulin-like growth factor 2)." (PMID 37373059, 2023). "The use of double promoter toxin vector H19-DTA-(IGF2)-P4-DTA exhibited superior inhibition towards pancreatic cancer, ovarian cancer, glioblastoma and HCC." (PMID 36246634, 2022). "Additionally, Brouwer-Visser et.al indicated that suppressing the expression level of IGF2 in ovarian cancer cells via employing RNA interference technology could elevate paclitaxel sensitivity and could restore sensitivity to both microtubule-stabilizing and destabilizing agents." (PMID 33768092, 2021). "It has been shown that upregulation of IGF2 drives chemoresistance to Taxol (paclitaxel), fluorouracil and CDDP, in ovarian cancer, esophageal cancer, and HNC, respectively." (PMID 34067117, 2021). "In ovarian cancer, an NSUN2/IGF2 signature has been identified, which has prognostic survival value, as patients with high NSUN2 expression and low IGF-II expression had significantly superior overall and disease progression-free survival." (PMID 32708015, 2020). "GPC3 mediates the synthesis of integral membrane proteins that interact directly with insulin like growth factor 2 (IGF2), which is considered to be an important growth factor in ovarian cancer." (PMID 32047514, 2019). "The model was calibrated and validated using an ovarian cancer cell line, OVCAR5, and then analyzed to determine the relative impact of IGF2R and IGFBPs on IGF2-mediated IGF1R activation." (PMID 26861122, 2016). "As we previously reported, upregulation of insulin-like growth factor 2 (IGF2) is an acute cellular response to Taxol treatment, and its expression modulates the response to Taxol in drug resistant ovarian cancer cell lines." (PMID 24932685, 2014). "Positive correlations were identified between elevated IGF2 expression and hypermethylation of CTCF binding sites at the H19 proximal imprint center in ovarian cancer." (PMID 19737423, 2009). "From the total of 34 ligand and receptor genes identified in these interactions, seven (COL1A1, ITGB5, COL1A2, FGFR2, FN1, IGF1, and IGF2) were consistently up-regulated and predicted worse overall survival in two additional cohorts (TCGA and GSE9891) of ovarian cancer patients." (PMID 36352420, 2022).
ovarian carcinoma (continued). "Hence, we presumed that TMED2 regulation of epithelial ovarian cancer proliferation, migration and invasion involves IGF1R/IGF2/PI3K/AKT pathway." (PMID 29212217, 2017). "Based on these laboratory and clinical data, we determined that IGF2 is a potential therapeutic target to ameliorate drug resistance in ovarian cancer, but to our knowledge, no prior in vivo validation studies have been done." (PMID 24932685, 2014). "Similarly experimentally induced paclitaxel resistance was associated with elevated IGF2 mRNA, while knockdown of IGF2, but not insulin-like growth factor 1 receptor (IGF1-R), restored sensitivity to paclitaxel in ovarian cancer cell lines." (PMID 41007637, 2025). "Two GEMM models were down-classified to the ‘low’ category, with one study reporting the accidental development of RMS in an ovarian cancer mouse model due to non-specific genetic manipulation, and the other study reporting IGF-2 overexpressing pelvic RMS with concomitant salivary carcinoma." (PMID 38371622, 2024). "Dr Gil Mor’s group identified a panel of 6 biomarkers, CA-125, osteopontin (OPN), insulin-like growth factor 2 (IGF-II), macrophage migration inhibitory factor (MIF), leptin and prolactin, which demonstrated a sensitivity of 95.3% and a specificity of 99.4% for the detection of ovarian cancer." (PMID 24116163, 2013). "In summary, IGF2 knockdown, but not selective IGF1R inhibition, effectively reverses drug resistance in a Taxol-resistant human ovarian carcinoma xenograft model." (PMID 24932685, 2014).
Beckwith-Wiedemann syndrome (66 papers, 2003 to 2026). Beckwith-Wiedemann syndrome (BWS) is a genetic disorder characterized by overgrowth, tumor predisposition and congenital malformations. "Maternal loss of imprinting (LOI) at the H19/IGF2 locus results in biallelic IGF2 and reduced H19 expression and is associated with Beckwith–-Wiedemann syndrome (BWS)." (PMID 34402430, 2021). "Beckwith-Wiedemann syndrome can be caused by disorders of methylation affecting imprinted genes within chromosome 11p15.5 containing IGF2 and CDKN1C, both of which appeared in our analyses." (PMID 33682876, 2021). "The IGF2 gene is implicated in syndromes associated with fetal under-growth (Silver-Russell syndrome) or over-growth (Beckwith-Wiedemann syndrome)." (PMID 33682876, 2021). "CTCF site-specific deletions were shown to be associated with imprinting in the IGF2/H19 locus, causing Beckwith-Wiedemann syndrome (BWS; OMIM 130650)." (PMID 33863876, 2021). "Patients with Beckwith-Wiedemann syndrome have overexpression of IGF-2 due to loss of the maternal locus, 11p15." (PMID 25889798, 2015). "IGF2 and H19 are both imprinted genes and loss of imprinting of the IGF2/H19 locus has been observed in the Beckwith-Wiedemann syndrome, a congenital overgrowth disorder." (PMID 24349121, 2013). "The abnormal phenomenon in CP2 and CP3 included an enlarged tongue (macroglossia), which is similar to Beckwith-Wiedemann syndrome, and is caused by aberrant methylation and expression of IGF2 in humans." (PMID 22393450, 2012). "Accurate DNA methylation of the IGF2/H19 locus is important for growth and disorders of imprinting mediated by DNA methylation in this region (Russell Silver and Beckwith Wiedemann syndromes) are associated with clear phenotypes of altered growth." (PMID 23148549, 2012). "In contrast, in Beckwith-Wiedemann syndrome, an IGF2 gene polymorphism has been associated with loss of imprinting of the maternal allele-specific methylation of the KCNQ1 gene." (PMID 22022277, 2011). "IGF2 imprinting defects also underlie Beckwith-Wiedemann syndrome which is characterized by overgrowth." (PMID 19924280, 2009). "Transgenic overexpression of the paternally expressed Igf2 gene increased fetal growth, and upregulation or downregulation of IGF2 via aberrant imprinting is associated with the overgrowth disorder Beckwith-Wiedemann syndrome and the growth retardation disorder Silver-Russell syndrome, respectively." (PMID 35938007, 2022). "Over-expression of IGF2 in humans appears to be responsible for the asymmetric organ and tissue overgrowth observed in Beckwith-Wiedemann syndrome, and its diminished expression appears to cause the reduced growth and bodily dysmorphism seen in Silver-Russell syndrome." (PMID 31251794, 2019). "In humans, pediatric undergrowth and overgrowth disorders, such as Silver-Russell and Beckwith-Wiedemann syndromes, respectively, are associated with corresponding alterations in levels of IGF2, and changes in IGF2/Igf2 gene expression influence tissue and organismal growth in pigs and mice." (PMID 31251794, 2019). "The imprinted gene IGF2 has a major role in mediating fetal growth and altered DNA methylation at the IGF2 DMRs is known to be associated with human syndromic growth disorders, including Silver Russell and Beckwith Wiedemann syndromes." (PMID 25630355, 2015). "Similarly, loss of DNA methylation imprinting in long non-coding H19 and neighboring IGF2 in the placenta is associated with Beckwith-Wiedemann Syndrome and increased prenatal and placental growth." (PMID 25675430, 2015). "In addition, IGF2 has been implicated in two imprinted human growth disorders, the overgrowth, Beckwith-Wiedemann syndrome (BWS) and the growth restricting Silver-Russell syndrome (SRS)." (PMID 24454871, 2014).
Beckwith-Wiedemann syndrome (continued). "The alteration of the imprinting status of an IGF2 allele (loss of imprinting, LOI) results in biallelic expression during embryonic growth, whereas IGF2 overexpression in mice causes prenatal or postnatal overgrowth that is similar to the symptoms of Beckwith-Wiedemann syndrome." (PMID 22393450, 2012). "Dysregulation of the H19/IGF2 cluster is associated with two growth disorders, Beckwith-Wiedemann syndrome (BWS) and Silver-Russell syndrome (SRS)." (PMID 36441651, 2022). "Beckwith-Wiedemann syndrome (BWS) is also associated with overexpression of IGF2 due to disruption of the 11p15 loci, including segmental UPD." (PMID 34803919, 2021). "Since, a methylation defect at the Igf2/H19 locus can result in imprinting disorders, and has been associated with Beckwith-Wiedemann syndrome, such gene dysregulation as a result of higher maternal FA may modulate epigenetic abnormalities in the pathogenesis of growth and development." (PMID 25629700, 2015). "The imprinting mechanism appears to be the same in humans, as some patients with Beckwith-Wiedemann Syndrome (BWS) show biallelic expression of IGF2 that is associated with the inheritance of maternally methylated or deleted ICRs." (PMID 24324735, 2013). "Aberrations of LIT1 expression, such as those caused by LOI, involving aberrant hypomethylation and activation of the normally silent maternal allele and LOI IGF2 have been observed in Beckwith-Wiedemann syndrome (BWS) and colorectal cancer." (PMID 19737423, 2009). "Global prenatal transgene Igf2 overexpression led to perinatal lethality, whole body overgrowth and other Beckwith-Wiedemann syndrome phenotypic determinants." (PMID 40880432, 2025). "Similarly, mutations in IGF2, an important growth factor in human development and growth, may cause abnormal growth and development, and potentially contribute to the onset of diseases such as Beckwith-Wiedemann syndrome or cancer." (PMID 38737102, 2024). "The importance of IGF signalling and imprinting for human fetal development is exemplified by characteristic overgrowth in Beckwith-Wiedemann syndrome (BWS), associated with excess IGF2 expression, and growth restriction in Silver-Russell syndrome (SRS) associated with loss of IGF2 expression." (PMID 38816743, 2024). "IGF2 expression occurs almost exclusively from the paternal allele, and imprinting defects that lead to expression from the maternal allele cause Beckwith-Wiedemann syndrome (BWS)." (PMID 26516454, 2015). "Loss of imprinting at the IGF2/ICR1/H19 domain has been reported in some cases of Beckwith-Wiedemann syndrome (BWS), which is associated with prenatal overgrowth, and with Silver-Russell syndrome (SRS), which is associated with profound pre- and post-natal growth failure." (PMID 26091021, 2015). "In humans, IGF2 upregulation is important in the pathogenesis of Beckwith-Wiedemann syndrome (BWS), which is characterized by somatic overgrowth that is similar to the large offspring syndrome in ruminants." (PMID 24397284, 2014). "In human, the phenotype related to the silencing of IGF2 is Silver Russell syndrome and H19 silencing is related to Beckwith Wiedemann syndrome." (PMID 23724794, 2013). "For example, hypermethylation of H19-DMR, which is the ICR of the IGF2/H19 imprinting domain at the 11p15.5 locus, is a cause of Beckwith-Wiedemann syndrome (BWS), the most common overgrowth syndrome characterized by occasional development of embryonal tumors, including hepatoblastoma." (PMID 24373183, 2013). "Aberrant imprinting of the IGF2/H19 locus on chromosome 11p15.5 has a crucial role in Beckwith-Wiedemann syndrome (BWS, OMIM #130650), Silver-Russell syndrome (SRS, OMIM#180860) and several human cancers." (PMID 22646060, 2012). "The overgrowth Beckwith-Wiedemann syndrome is associated with hypermethylation of the ICR, leading to increase of IGF2 and decrease in H19 activity." (PMID 23148549, 2012).